PRAMEF26 (PRAME family member 26)
Tractability: No criterion of Open Targets' tractability assessment is met for any kind of drug.
Gene: Protein-coding gene on chromosome 1 (13,148,905 to 13,158,116, reverse strand). Ensembl gene ENSG00000280267.
Gene Ontology:
Molecular function: ubiquitin-like ligase-substrate adaptor activity
Biological process: proteasome-mediated ubiquitin-dependent protein catabolic process; negative regulation of apoptotic process; negative regulation of cell differentiation; negative regulation of DNA-templated transcription; positive regulation of cell population proliferation
Cellular component: Cul2-RING ubiquitin ligase complex; cytoplasm
Homologues: Orthologues: mouse Pramel13 (45% identical), rat Pramef12 (44% identical), rat Pramef8 (43% identical), mouse Pramel12 (43% identical), mouse Pramel15 (43% identical), rat LOC120103107 (42% identical), rat Pramef20 (42% identical), mouse Pramel16 (42% identical), mouse Pramel31 (42% identical), rat Pramef5 (42% identical), rat Pramef20l1 (42% identical), rat Pramel36l1 (42% identical), and 78 more. Paralogues in human: PRAMEF25 (100% identical), PRAMEF15 (97% identical), PRAMEF5 (96% identical), PRAMEF6 (96% identical), PRAMEF4 (96% identical), PRAMEF9 (96% identical), PRAMEF11 (96% identical), PRAMEF27 (96% identical), PRAMEF20 (82% identical), PRAMEF12 (62% identical), PRAMEF8 (61% identical), PRAMEF7 (61% identical), and 12 more.